TCF12 (transcription factor 12)
Diseases named in the same sentence as TCF12 in open-access papers (continued):
Sharing a sentence is not in itself a finding about the gene and the disease.
tumor (continued). "Since epithelial-mesenchymal transition (EMT) is a crucial event in the progression of tumor metastasis 28, we further investigate whether TCF12 regulated the EMT markers of HCC cells by western blot." (PMID 31534521, 2019). "In addition, TCF12 participates in the angiogenesis of endothelial cells in the tumor microenvironment via regulation of CXCL12 and CXCR4-mediated bFGF expression." (PMID 31534521, 2019). "In addition, the results from our HCC xenograft tumor model demonstrated that TCF12 overexpression enhanced tumor formation and lung metastasis, whereas TCF12 knockdown suppressed hepatocarcinogenesis." (PMID 31534521, 2019). "Moreover, CXCR4, with its ligand CXCL12, played a critical role in tumor progression induced by TCF12 via activation of the MAPK/ERK and PI3K/AKT signaling pathways." (PMID 31534521, 2019). "Additionally, higher serum HSP90α levels were measured from CRC patients with an elevation of TCF12 expression in their tumor tissues." (PMID 29435158, 2018). "To test this hypothesis, we measured the expression levels of cyclin D1 (CCND1), one of the key regulators of the G1 to S phase transition.Protein levels of CCND1 were significantly lower in the TCF12 KO tumor cells compared to control and scramble tumor cells." (PMID 37046694, 2023). "Notably, significant functional differences are predicted between the long or short isoforms of TCF12, OSBPL1A, TRAK1, CHEK1, ANK3, LMO7 and SCIN indicating that the observed tumor associated changes in TSS usage probably have an impact on the growth properties of the neoplastic cells." (PMID 21999571, 2011). "Representative protein expression of MEOX2, PHYHIP, RBBP8, ST18, TCF12, and THRB in tumor tissues was demonstrated based on immunohistochemical analysis in the HPA database." (PMID 40869909, 2025). "The work presented here reveals a novel key role for the transcription factor TCF12 in the regulation of proliferation of GBM cells and tumor progression." (PMID 37046694, 2023). "Five potential tumor neoantigens (LRP1, TCF12, DERL3, WIPI2, and TSHZ3) were identified in GBM by selecting genes both with abnormal alternative splicing (upregulated) and gene frameshift mutations, in which LRP1 was significantly associated with APCs." (PMID 37978542, 2023). "Knockdown of TCF12 significantly impaired the growth of YUMM1.7 tumors, as evidenced by slower tumor growth kinetics and smaller tumor size at the endpoint, in line with a lower proliferation index by Ki67 IHC." (PMID 37760480, 2023). "To this end, we injected 50,000 cells from each of control, scramble and TCF12 KO GL261 cells into immunocompetent B6 mice (four mice in each group) and monitored tumor initiation and progression by serial MRIs." (PMID 37046694, 2023). "To test this, we performed intracranial injections of 50,000 cells of either TCF12-overexpressing vector (OE) or empty vector (EV) GL261 cells into immunocompetent mice and monitored tumor appearance by MRI." (PMID 37046694, 2023). "In GBC, HDAC1 was first shown to interact with the transcription factor TCF-12, driving GBC tumor invasion and leading to poor prognosis." (PMID 37760477, 2023). "To further prove a direct role for TCF12 in the regulation of proliferation of tumor cells, we overexpressed TCF12 in GL261 tumor cells and restored it to TCF12 KO GL261 tumor cells." (PMID 37046694, 2023). "On the other hand, overexpression of TCF12 greatly accelerated YUMM1.7 tumor progression, consistent with more Ki67+ cells in the tumor tissues." (PMID 37760480, 2023). "Transcription factor 12 (TCF12) is a member of the helix-loop-helix protein family and serves either as an oncogene or tumor suppressor gene in multiple human cancers." (PMID 33413401, 2021). "Although TCF12 is an oncogenic molecule in CRC and some other cancers, its function as a tumor suppressor has become more evident in a subset of malignancies." (PMID 31534521, 2019).
tumor (continued). "Both HDAC1 and TCF-12 have a high-expression in GBC and Liver-metastasis tissues contrast with Non-tumor tissues." (PMID 27092878, 2016). "These associations remained statistically significant even after being adjusted for tumor metastasis and patients’ age, suggesting that TCF12 could collaborate with MALAT1 to exacerbate CRC patients’ OS independently of patients’ age and tumor metastasis." (PMID 39768127, 2024). "Overall, the LINC00606/miR-486-3p/TCF12/ATP11B axis is involved in the regulation of GBM progression and plays a role in tumor regulation at transcriptional and post-transcriptional levels primarily through LINC00606 sponging miR-486-3p and targeted binding to ATP11B." (PMID 38725030, 2024). "However, the in vivo role of TCF12 in IDH-WT GSCs, tumor formation, and progression has yet to be investigated in any human patient-derived lines or in vivo murine GBM models." (PMID 37046694, 2023). "Moreover, our results indicate that the interaction between TCF12 and the BRAF pathway is crucial in mediating the tumor’s response to BRAF-targeted therapy." (PMID 37760480, 2023). "As TCF12 regulated CXCR4 and CXCL12 expression, an in vitro HUVECs tube formation assay was conducted to explore whether TCF12 plays a functional role in tumor angiogenesis." (PMID 31534521, 2019). "In the present study, our functional experiments revealed that TCF12 could enhance HCC cell proliferation and migration in vitro and tumor formation in vivo." (PMID 31534521, 2019). "The short TCF12 isoform was expressed in half of the patients, and solely in cancer cells or, interestingly, cancer derived stroma, thus, confirming the tumor-specificity we observed in non-LCM samples." (PMID 21999571, 2011). "We found that TCF12 mRNA was highly upregulated in GBM tumor cells compared to nontumor cells." (PMID 37046694, 2023). "Quantification of tumor weight (liver with xenograft) showed that Li7 and SMMC-7721 cells overexpressing TCF12 generated larger tumor masses than did the corresponding control cells, and the xenograft tissues maintained high expression levels of TCF12 in the TCF12-overexpressing group." (PMID 31534521, 2019). "Therefore, we used qRT-PCR to determine the TCF-12 expression levels in tumor and paired non-tumour tissues obtained from 73 patients with GBC." (PMID 27092878, 2016). "While there are no mutagenesis data on the homologous domains of Tcf12, the truncated Tcf12 transcript expressed in tumor 3095 would lack the AD1 domain but have an intact AD2 domain, which could result in attenuated transactivation." (PMID 19461887, 2009). "MEOX2 and PHYHIP, showed no significant protein expression in tumor tissues; the THRB showed “low intensity”, RBBP8 and ST18 showed “medium intensity”, and, interestingly, the TCF12 showed “high intensity”." (PMID 40869909, 2025).
cancer (37 papers, 2010 to 2026). A tumor composed of atypical neoplastic, often pleomorphic cells that invade other tissues. "Though class I bHLH TFs (TCF3, TCF4, and TCF12) are important for cancer, development, and immunity, and associated with neural disorders, how they functionally contribute to these processes is poorly understood." (PMID 39119816, 2025). "Besides neurodevelopmental consequences associated with TCF12 mutations, it was also suggested to be used as a biomarker for prognosis in various cancer types." (PMID 39036055, 2024). "Somatic genetic alterations of TCF12 (overexpression or loss-of-function) could alter progression, occurrence of metastasis, and prognosis in various cancer types." (PMID 39036055, 2024). "This could be explained by the de novo synthesis of the short TCF12 isoform in a subset of cancers, as the mRNA encoding the long variant was expressed at equivalent levels in normal and cancer samples." (PMID 21999571, 2011). "This study identifies a new function for class I bHLH transcription factors (e.g., TCF3, TCF4, and TCF12) that are important in cancer and development." (PMID 39119816, 2025). "The expression of TCF12 in cancer was initially analyzed using data from the TCGA database, which showed that TCF12 is generally upregulated across various cancer types." (PMID 40190273, 2025). "TCF12 governs essential cellular behaviors, impacting neurogenesis, craniofacial development and cancer development." (PMID 38739758, 2024). "CYT-low COAD tumors contained significantly more cancer genes harbored within chromothriptic regions (TCF12, NF1, ERBB2, JUN, JAK1 and BCL10)." (PMID 34316699, 2021). "TCF12 is believed to be a transcription factor and has been reported to have a close relationship with invasion of cancer." (PMID 29069829, 2017). "TCF12 protein expression was upregulated in cancer samples and correlated with progression free survival." (PMID 21999571, 2011). "The changes observed for CHEK1, OSBPL1A and TCF12 were confirmed in several other cancer types indicating that the change in TSS usage is a general mechanism in cancer biology." (PMID 21999571, 2011). "Others, such as TCF12 and NIPBL, are less commonly associated with cancer or drug resistance; TCF12 is classified as a lower-confidence cancer gene in OncoKB, and NIPBL is not listed, suggesting potential novel roles in mediating transcriptional reprogramming." (PMID 41492468, 2026). "Furthermore, TCF12 displayed brain tissue-specific expression, and pan-cancer enrichment analysis also shows that TCF12 expression in LGG and GBM was high." (PMID 38725030, 2024). "Although the overexpression of MALAT1 or TCF12 has been independently linked to poorer prognosis in CRC patients, investigations conducted across different cancer types or patient cohorts may have contradictory results." (PMID 39768127, 2024). "Disclosing the TCF12 signaling axis in OPN-induced EndoMT may shed light on the unknown mechanism of cancer-related EndoMT." (PMID 29435158, 2018). "TCF-12 have been reported close relationship with invasion of cancer." (PMID 27092878, 2016). "In addition to cancer, TCF12 is involved in the regulation of other diseases." (PMID 40166462, 2025). "Indeed, TCF12 regulates a wide range of cellular processes, e.g., the mesenchymal transition of epithelial/endothelial cells, fibroblast activation and extracellular matrix remodeling, the drug uptake of cancer cells, and muscle development." (PMID 39768127, 2024). "The TCF12 (transcription factor 12) gene is involved in NTRK signaling and DNA binding, impacting gene transcription related to cancer progression." (PMID 39589950, 2024). "First, IHC analysis showed a significant difference in the total protein level of TCF12 and OSBPL1A between normal and cancer samples consistent with the mRNA expression pattern we observed." (PMID 21999571, 2011).
cancer (continued). "This revealed a sub-network linking eight transcriptional regulators of which most already have been related to cancer progression, including HDAC2, BPTF, BRF1, TAF11, TCF12, and FOS31,32, but also a prominent role for SMADs that are normally driven by TGF-β33." (PMID 31278301, 2019). "Notable alterations in human cancer gene orthologs impacted by SVs in single cases include an ARHGEF12 inversion, a BIRC3 inversion, a CLPTM1L-TERT translocation, a DDIT3 inversion, a MYO5A translocation, and a TCF12 inversion." (PMID 30188888, 2018). "In the human network, we also found a significant enrichment for developmental signaling pathways, exemplified by proteins like ID3 and UNC45A, which are involved in cell differentiation and proliferation, and which interact with the cancer drivers MAX and TCF12 respectively." (PMID 26576632, 2015).
adenocarcinoma (1 paper, 2011). A common cancer characterized by the presence of malignant glandular cells. "To investigate the association between recurrence-free survival and TCF12 or OSBPL1A expression, we used a TMA containing biopsies from 268 stage II adenocarcinomas." (PMID 21999571, 2011).
hematological cancer (1 paper, 2022). "Analysis by LC-MS/MS identified more than 600 Lmo2-interacting molecules in physiological LPs, including the previously reported components of Lmo2 complexes in hematological cancer cell lines, Lyl1, Tal1, Ldb1, Tcf12, Tcf3, and Cbfa2t3 (also known as ETO2 or MTG16)." (PMID 36126774, 2022).
neurodevelopmental disorder (1 paper, 2024). A behavioral and cognitive disorder with onset during the developmental period that involves impaired or aberrant development of intellectual, motor, or social functions. "TCF12 is essential for neuronal migration in cortical development, and RORA play crucial roles of cerebellar and systemic abnormalities observed in neurodevelopmental disorders." (PMID 39184089, 2024).
TCF12 also shares sentences with these, for which no sentence is quoted: craniosynostosis syndromes (3 papers); infection (3); Muenke syndrome (3); Crouzon syndrome (2); hypogonadotropic hypogonadism (2); Obesity (2); T-cell acute lymphoblastic leukaemia (2); acanthosis nigricans (1); Alagille syndrome (1); Apert syndrome (1); autism spectrum disorder (1); Boston type craniosynostosis (1); brain cancer (1); Burkitt lymphoma (1); cardiac hypertrophy (1); cardiovascular diseases (1); cervical adenocarcinoma (1); clear cell renal cell carcinoma (1); Diamond-Blackfan anemia (1); dysplasia (1); gallbladder cancer (1); Huntington disease (1); Jackson-Weiss syndrome (1); learning disability (1); lipoma (1); long QT syndrome (1); macular degeneration (1); metastatic tumors (1); Myelodysplasia (1); myeloid leukemia (1).
A further 10 diseases each share a sentence with TCF12 in 1 paper.